NF1 (neurofibromin 1)
Diseases named in the same sentence as NF1 in open-access papers (continued):
Sharing a sentence is not in itself a finding about the gene and the disease.
melanoma (continued). "In the case of the analyzed NF1-associated melanoma, DNA of seven consecutive microdissected melanoma sections representing approx. 3500 tumor cells was pooled and distributed into 184 individual PCR tubes." (PMID 16961930, 2006). "In NF1-associated melanoma, LOH has been reported only once in a melanoma displaying an atypical anal localization." (PMID 16961930, 2006). "The potential association between NF-1 and malignant melanoma has been the source of controversy in the medical literature." (PMID 15363097, 2004). "Our case provides another framework for the discussion of the potential association between NF-1 and malignant melanoma." (PMID 15363097, 2004). "Additionally, individuals with NF1 loss have a higher incidence of melanoma, with earlier diagnoses and thicker tumors, further emphasizing the need for cautious monitoring in this population." (PMID 40867277, 2025). "Additionally, the molecular heterogeneity of COM has been documented in previous studies, identifying subtypes with profiles similar to human melanomas with BRAF mutations or NF1 deficiency." (PMID 40647405, 2025). "We identified DE genes that were produced by Nf1 heterozygous loss in melanoma driven by GNAQQ209L." (PMID 39804140, 2025). "Additionally, mutations in the NF1 gene, often observed in melanomas arising on chronically sun-exposed skin, lead to hyperactivation of the NRAS–MAPK pathway and increased resistance to apoptosis." (PMID 40507265, 2025). "Pathogenic NF1 variants appeared at low frequency except in malignant melanoma and glioma (10%)." (PMID 41220108, 2025). "NF1-mutated melanomas also tend to be immunologically “hot”." (PMID 41465101, 2025). "The NF1-loss melanoma subtype is characterized by distinct clinical and biological features." (PMID 40867277, 2025). "This study investigated whether NF1 loss can collaborate with oncogenic GNAQ to promote melanoma in the dermis or eyes, in which the Gαq pathway is almost always activated." (PMID 39804140, 2025). "In addition to other aberrations, NGS analysis of both tumour manifestations revealed NF1 gene mutations, suggesting a diagnosis of undifferentiated melanoma." (PMID 41073541, 2025). "Melanomas with NF1 mutations exhibit a higher mutational burden and a strong UV mutation signature." (PMID 40867277, 2025). "For example, BRAF and NRAS mutations are prevalent in superficial spreading and nodular melanomas, NF1 loss is associated with chronic sun-damaged melanomas, KIT mutations are more common in acral and mucosal disease, and GNAQ/GNA11 mutations characterize uveal melanoma." (PMID 41283484, 2025). "In particularly difficult cases, molecular analysis may be helpful; TMMs are known to exhibit highly similar mutational landscapes to conventional melanomas (e.g., mutations in NF1, NRAS; variable BRAF V600E)." (PMID 40090763, 2025). "One of the primary research objectives of this study was to determine whether Nf1 loss would accelerate tumorigenesis of intradermal melanoma in mice expressing GNAQQ209L." (PMID 39804140, 2025). "Therefore, melanomas with NF1 deficiency are particularly difficult to treat with conventional inhibitors of the MAPK pathway." (PMID 40872623, 2025). "NF1 mutations are also more frequent in desmoplastic melanomas." (PMID 40125165, 2025). "The high frequency of BRAF and NRAS mutations in particular provides important insights into the molecular heterogeneity of melanomas and potential sensitivity to targeted therapies, while NF1 and PTEN mutations further illustrate the diversity of driver alterations in this population." (PMID 41142596, 2025). "Furthermore, 15% of NF1 loss-of-function mutant melanomas harbor concomitant class III C600 BRAF mutations." (PMID 39727691, 2024).
melanoma (continued). "Often, class III BRAF mutants in tumors co-exist with RAS mutations or neurofibromin 1 (NF1) deletions (melanomas) or RTK upregulation (lung and colorectal cancers), highlighting the need for concurrent mechanisms for sustaining RAS activation despite ERK-dependent feedback." (PMID 38731852, 2024). "It is possible that NF1 loss and subsequent increased ras/mitogen-activated protein kinase signaling in the cNF led to increased proliferation of surrounding melanocytes that ultimately developed the melanoma." (PMID 39687068, 2024). "The NF1 gene is frequently mutated in sporadic human tumor types including melanoma." (PMID 39687068, 2024). "Notably, most of the NF1 mutations associated with melanoma result in loss of function in the NF1 gene, classifying it as a tumor suppressor." (PMID 38732242, 2024). "Data are available for NF1-mutated sporadic cancers—which mainly include melanoma." (PMID 38341500, 2024). "Furthermore, melanomas with neurofibromin 1 (NF1) mutations are associated with advanced patient age and have a poorer prognosis compared to other mutation patterns." (PMID 38474231, 2024). "Studies have shown that NF1-mutated melanomas have increased sensitivity to MEK inhibitors." (PMID 38534309, 2024). "Typically, NF1 mutations are found in melanomas that lack mutations of BRAF and NRAS." (PMID 38247727, 2024). "Up to 12% of all melanomas display multiple neurofibromin 1 (NF1) mutations." (PMID 39126091, 2024). "This showcases the high burden of the UV mutational signature in NF1-mutant melanomas." (PMID 38247727, 2024). "Recently it has been reported that knockout of PRKAA2 in NF1-deficient melanoma cells promoted anchorage-independent growth in vitro, as well as growth as xenografts in immunodeficient mice in vivo, suggesting that AMPK-α2 can act as a tumour suppressor in that context." (PMID 37962491, 2023). "Patients with NRAS- and NF1- mutated melanomas tend to have a worse prognosis." (PMID 37900283, 2023). "Following BRAF, NRAS, and NF1 comprise the next most common mutations identified in melanoma." (PMID 37900283, 2023). "Emerging evidence suggests that somatic NF1 mutations in melanoma may impact the tumor microenvironment and immune response." (PMID 37504268, 2023). "On the contrary, NF1 mutation was considered a favorable marker for ICI-treated melanoma patients." (PMID 36973365, 2023). "NF1 alterations are more frequent in melanomas associated with high CSD." (PMID 37958863, 2023). "The results indicated NF1 patients had roughly 30% higher bioavailability compared with melanoma patients, but the underlining mechanism remains unclear." (PMID 36755948, 2023). "Moreover, 13–17% of all melanomas, with loss-of-function mutations, inactivate the tumor suppressor Neurofibromin 1 (NF1), a negative regulator of RAS signal transduction." (PMID 35163453, 2022). "Melanomas that arise due to sun exposure are generally dominated by NF1 and NRAS mutations." (PMID 34110110, 2022). "Importantly, a much greater difference in mutation load exists between other melanoma genetic subtypes: on average, NF1-driven tumors display the highest and triple-WT tumors the lowest mutation rates of all four subtypes." (PMID 35234863, 2022). "The activation of this pathway in melanoma also may be initiated by mutated NRAS GTPase or NF1 (neurofibromin) deficiency." (PMID 35053262, 2022). "NF1 mutations are more frequent in acral and mucosal melanomas." (PMID 36614156, 2022). "Non-CSD melanomas develop typically in younger patients and predominantly carry BRAF mutations, while CSD melanomas have a higher mutation burden, more often contain NF1, NRAS or KIT mutations and affect older people at the distal extremities and head and neck region." (PMID 35328746, 2022).
melanoma (continued). "Additionally, NRAS and NF-1 mutations in canine melanoma have also been reported, but at a very low frequency." (PMID 36686160, 2022). "Additionally, NRAS mutations are found in 15–30% of melanoma patients, and NF1 mutations are found in 12–18% of all melanomas." (PMID 34066966, 2021). "Since 80% of human cutaneous melanomas harbor activating hot-spot mutations in either BRAF or NRAS (e.g., BRAFV600, NRASG12, or NRASQ61), we examined the nf1/pten-mutant zebrafish melanomas for spontaneous mutations at equivalent sites in the zebrafish orthologues." (PMID 34331013, 2021). "Furthermore, cleaved caspase 3 in WM-3246 cells treated with the three-drug combination but not with sirolimus alone, validating the induction of apoptosis by co-inhibition of BCL2 and MCL1 in sirolimus-sensitized NF1/PTEN-deficient human melanoma cells." (PMID 34331013, 2021). "In contrast, the CSD melanomas had a higher frequency of mutations than the nevogenic melanomas in NF1 (14/37, 37.8% vs. 6/82, 7.3%; p < 0.001), ROS1 (10/37, 27.0% vs. 4/82, 4.9%; p = 0.001), GNA11 (4/37, 10.8% vs. 1/82, 1.2%; p = 0.032), and RAC1 (6/37, 16.2% vs. 1/82, 1.2%; p = 0.004)." (PMID 34680367, 2021). "Several prominent genes mutated in CSD melanomas included NF1, ROS1, GNA11, and RAC1." (PMID 34680367, 2021). "The third most common mutated gene in malignant melanomas is the tumor suppressor gene NF1." (PMID 34576054, 2021). "The rate of NF1 mutations is comparable across cutaneous and mucosal melanomas." (PMID 35008570, 2021). "We did not observe a correlation between MITF expression and the most common BRAF, NRAS, and NF1 mutations found in melanoma, indicating that the gene expression changes observed are controlled via transcriptional regulation, directly or indirectly imposed by MITF." (PMID 33438577, 2021). "In earlier studies, the loss of the tumor suppressor NF1 has been observed in melanomas." (PMID 34063141, 2021). "This well-tolerated drug combination potently and synergistically induces apoptosis in both zebrafish and human NF1/PTEN-deficient melanoma cells, providing preclinical evidence justifying an early-stage clinical trial in patients with NF1/PTEN-deficient melanoma." (PMID 34331013, 2021). "Overall, the frequency of RAS, BRAF or neurofibromin 1 (NF1) mutations resulting in the activation of the MAPK pathway seems to be lower in ALM than in other subtypes of melanoma, and other drivers such as KIT, PAK1 and SPRED1 may be more important." (PMID 32330367, 2021). "NF1 mutations were found in up to 17% of samples in the Melanoma Genome Project report." (PMID 33807778, 2021). "Exome sequencing studies demonstrated NF1 mutations in 12–30% of melanoma." (PMID 34680938, 2021). "Additionally, desmoplastic melanoma has a high frequency of NF1 mutations, distinct from conventional melanoma." (PMID 33095773, 2020). "RASA2 mutations co-occurred in NF1 mutant melanomas that were BRAF-RAS wild type, in a WES study of 213 melanoma samples (62 cell lines and 151 melanomas); 12.2% (26/212) of melanomas were NF1-mutant/BRAF-RAS-wild-type and nine of them harbored co-mutations in RASA2 (2 nonsense and 3 R551C)." (PMID 32850962, 2020). "However, as NF1 mutations can be found in melanomas with concurrent BRAF or NRAS hotspot mutation, a three-group classification of melanoma (mutant BRAF, mutant RAS, non-BRAFmut /non-NRASmut) has been proposed." (PMID 32850962, 2020).
melanoma (continued). "When excluding AKT1-mutated patients and considering only NF1 mutations with more deleterious effects (nonsense, frameshift, and splicing variants), the most frequent cancer types are non-small cell lung cancer (12%), glioma (10%), and melanoma (9%)." (PMID 32858845, 2020). "Interestingly, in almost 10% of melanomas NF1 mutation co-occurs with RAS and BRAF alterations, suggesting a role for NF1 in controlling other pathways in addition to Ras-MAPK." (PMID 33096593, 2020). "In agreement, we observed marked elevation of glycolysis in addition to high OXPHOS, as shown by higher basal OCR, ATP-R, and activity levels of OXPHOS complexes, in three out of four of our melanoma cell lines (a BRAF/NRAF/NF1-wild-type and two BRAF-mutated melanoma cell lines) compared to HDFs." (PMID 33007949, 2020). "It seems that mutations in the NF1 gene co-occur with BRAF mutations in melanomas and may also play a role in acquiring resistance to BRAF inhibitors." (PMID 32605090, 2020). "Similarly, RASA2 gene alterations co-occur with NF1 mutation in melanoma, where RASA2 is mutated in about 5% of patients, leading to Ras signaling activation." (PMID 33096593, 2020). "Of interest, NF1 mutations may also be found in melanoma, but some studies suggest that targeting them with MEK inhibitors would be ineffective (though there may be exceptions)." (PMID 32066498, 2020). "A poorer OS for NF1-mutated subtype melanoma has also been described." (PMID 32850962, 2020). "NF1 mutations are present in <15% of melanoma cases and may be present together with NRAS/BRAF mutations." (PMID 32054078, 2020). "It should be noted that these observations could be influenced by the fact that both RAC1P29S/L and NF1 mutations tend to occur preferentially in highly mutated melanomas carrying a UV mutational signature." (PMID 31257073, 2019). "Mutations inactivating NF1 were reported in approximately 50% of melanomas." (PMID 31717496, 2019). "Thus, whereas mutual exclusivity of NF1-loss, in combination with previous experimental data, support NF1 as a strong oncogenic driver in lung adenocarcinoma and melanoma, the general oncogenic role of RASGAP deficiency in CRC remains inconclusive." (PMID 30858928, 2019). "NF1 mutated melanomas may respond to MEK inhibitor treatment as suggested by preclinical studies and a case report." (PMID 31500314, 2019). "Moreover, loss of NF1 expression has been observed in lung adenocarcinomas and melanomas that are resistant to treatment with EGFR and BRAF inhibitors, respectively." (PMID 30858928, 2019). "We found that when melanoma cells harboring wild-type NF1 alleles or melanoma cell lines with a heterozygous NF1 mutation in one allele and the other allele is intact were treated with combination of Calpain inhibitor I and Trametinib, a clear synergistic effect was observed." (PMID 30131853, 2018). "NF1 loss was previously shown to drive resistance to many different drugs in melanoma." (PMID 30131853, 2018). "This combination might therefore have a therapeutic potential not only in melanoma cells harboring wild type NF1 alleles, but also in melanoma cells harboring only one NF1 wild type allele." (PMID 30131853, 2018). "Importantly, NF1 stabilization was also observed in two NF1 mutant melanoma cells that harbor missense mutations in one of the NF1 alleles: 108T (p.H1721Q) and 76T (p.P1667S)." (PMID 30131853, 2018). "In the mucosal melanomas studied here, 9 out of 13 cases carried NF1 LoF mutations (69.2%)." (PMID 28380455, 2017). "However, NF1 somatic mutations are found in a range of cancers, and it is the third common driver mutation in melanoma found in nearly 14% of tumors." (PMID 29276510, 2017). "NF1 has been pinpointed as an important melanoma‐associated gene in previous studies." (PMID 28267273, 2017). "Although mutational mechanisms may differ, these studies and our data support NF1 mutations being highly relevant in melanoma subgroups that rarely harbor BRAF or NRAS mutations." (PMID 28380455, 2017).
melanoma (continued). "The analysis of the clinical parameters showed that NF1-mutated melanomas have a poor survival and an increased risk of death from melanoma, and these findings remained significant after adjustment for various important patient’s parameters such as age, gender, and lesion type." (PMID 29156643, 2017). "The majority of NF1-mutated melanomas occur in males, with older age at diagnosis." (PMID 29156643, 2017). "It is important to underline the high frequency of NF1 mutations among desmoplastic melanomas." (PMID 29156643, 2017). "Furthermore, on the basis of analyses of somatic co-mutation patterns in the TCGA data sets (cBio Portal for Cancer Genomics), 9.6% of melanomas with NF1 mutations also have mutations in BRAF, NRAS or RAF1." (PMID 28637487, 2017). "Collectively, these results highlight that NF1 mutation may harbor prognostic information in the metastatic setting of melanoma." (PMID 28267273, 2017). "BRAF/NRAS wild-type and NF1 mutant melanomas are strongly associated with UV damage, as evidenced clinically by the higher degree of solar elastosis and, at a molecular level, by a high proportion of C > T transitions at pyrimidine dimers and more frequent tandem CC>TT transitions." (PMID 28637487, 2017). "Also, a report on whole‐exome sequencing identified NF1 as the third most frequently mutated gene in melanoma after BRAF and NRAS, occasionally concurrently with other RASopathy gene mutations." (PMID 28267273, 2017). "The same group of investigators explored the NF1-mutated melanoma subgroup in detail." (PMID 29156643, 2017). "Most of the NF1 mutations observed in mucosal melanomas are inactivating mutations." (PMID 29156643, 2017). "In addition, all 26 NF1 mutant BRAF-RAS wild-type melanomas carried mutations in other known RASopathy genes, including RASA2, PTPN11, SOS1, RAF1 and SPRED1." (PMID 28637487, 2017). "In addition, NF1 mutations or suppression occur in human melanomas that harbor concurrent BRAF mutations." (PMID 24743024, 2014). "Loss of NF1 in malignant melanoma cell lines was reported soon after discovery of the NF1 gene in the early 1990s, but it was only recently that comprehensive genomic characterization of melanomas was performed." (PMID 25026295, 2014). "Somatic NF1 mutations have also been reported in melanoma specimens harboring BRAF mutations." (PMID 25026295, 2014). "The importance of a neurogenic differentiation pattern for NF1-associated melanoma genesis is further demonstrated by the detection of frequent NF1 allele loss in desmoplastic neurotropic melanoma which may display neural features and markers." (PMID 16961930, 2006). "The data suggested loss of the maternal microsatellite allele in the melanoma and probably inactivation of the maternal wild-type NF1 gene by deletion but false positive LOH due to stochastic errors induced by PCR could not be excluded." (PMID 16961930, 2006). "In the case of the analyzed NF1-associated melanoma, 29 alleles could be detected in DNA obtained by microdissection of approx. 3500 cells." (PMID 16961930, 2006). "Mutations or LOH at the NF1 gene are rare (≈5%) in typical malignant melanoma but could be demonstrated in 67% of desmoplastic neurotropic melanoma which represents a rare melanoma variant." (PMID 16961930, 2006). "In this study we could analyze a typical superficial spreading melanoma of a 15-year-old boy with NF1 for loss of heterozygosity (LOH) within the NF1 gene." (PMID 16961930, 2006). "Additionally, neurofibromin 1 (NF1) mutations have emerged as another distinct melanoma subtype." (PMID 40868149, 2025). "Also associated with an older age group and high CSD are melanomas with somatic NF1 mutations." (PMID 38247727, 2024). "Therefore, testing for this mutation may be particularly useful for diagnosing dedifferentiated melanomas as they also tend to occur on highly sun-exposed skin and are frequently NF1 mutated." (PMID 37373134, 2023).